SLC2A11 (solute carrier family 2 member 11)
Description:
Facilitative glucose transporter.
Synonyms: GLUT11; GLUT10
Tractability: Antibody: UniProt places it where antibodies can reach, with high confidence; its Gene Ontology location is reachable by antibodies, with high confidence; UniProt predicts a signal peptide or a membrane-spanning region. PROTAC: ubiquitination databases record sites on it.
Gene: Protein-coding gene on chromosome 22 (23,856,703 to 23,886,312, forward strand). Ensembl gene ENSG00000133460.
Subcellular location: Cell membrane
Subcellular location (Human Protein Atlas): Cell Junctions; Nucleoplasm
Pathways (Reactome):
Transport of small molecules: Cellular hexose transport
Gene Ontology:
Molecular function: D-glucose transmembrane transporter activity; fructose transmembrane transporter activity; sugar transmembrane transporter activity; transmembrane transporter activity
Biological process: D-glucose transmembrane transport; fructose transmembrane transport; dehydroascorbic acid transport; hexose transmembrane transport; transmembrane transport
Cellular component: plasma membrane; membrane
Genetic constraint (gnomAD): Loss-of-function variants: 45 observed, 50.21 expected, observed/expected ratio (o/e) 0.9, 90% interval 0.7 to 1.15. The upper end of that interval is the gene's LOEUF score, 1.15, which puts it in group 5 of 6, group 1 being the genes least tolerant of losing a copy. Missense variants: 582 observed, 649.29 expected, observed/expected ratio (o/e) 0.9, 90% interval 0.84 to 0.96. Synonymous variants: 261 observed, 277.58 expected, observed/expected ratio (o/e) 0.94, 90% interval 0.85 to 1.04.
Homologues: Orthologues: macaque MIF (94% identical), pig SLC2A11 (83% identical), dog SLC2A11 (82% identical), chimpanzee SLC2A11 (81% identical), guinea pig SLC2A11 (80% identical), rabbit SLC2A11 (60% identical), tropical clawed frog slc2a11 (60% identical), zebrafish slc2a11a (46% identical), Drosophila melanogaster sut2 (29% identical), Drosophila melanogaster CG7882 (27% identical), Drosophila melanogaster sut1 (27% identical), Caenorhabditis elegans fdgt-1 (26% identical), and 38 more. Paralogues in human: SLC2A7 (39% identical), SLC2A5 (39% identical), SLC2A9 (38% identical), SLC2A1 (35% identical), SLC2A4 (35% identical), SLC2A3 (33% identical), SLC2A14 (32% identical), SLC2A2 (32% identical), SLC2A8 (24% identical), SLC2A13 (24% identical), SLC2A10 (23% identical), SLC2A6 (22% identical), and 1 more.
Diseases named in the same sentence as SLC2A11 in open-access papers:
SLC2A11 is named in the same sentence as 15 diseases in open-access papers, as found by Europe PMC text mining. Sharing a sentence is not in itself a finding about the gene and the disease. The quoted sentences say what the papers report.
bladder cancer (6 papers, 2023 to 2025). "SLC2A11–MIF modulates bladder cancer cell proliferation and metastasis through a PTBP1‐dependent mechanism." (PMID 39156764, 2024). "Overall, our findings revealed a significant fusion protein orchestrated by the SLC2A11–MIF–PTBP1 axis that governs mRNA stability during the multistep progression of bladder cancer." (PMID 39156764, 2024). "In previous investigations, ten highly prevalent chimeric RNAs were identified, among which SLC2A11–MIF exhibited a greater frequency of detection in bladder cancer tissues than previously reported gene fusions." (PMID 39156764, 2024). "To explore the impact of SLC2A11–MIF on bladder cancer progression, we utilized specific small interfering RNAs (siRNAs) to effectively suppress SLC2A11–MIF expression." (PMID 39156764, 2024). "In conclusion, these results suggest that the upregulation of the SLC2A11–MIF transcript is a prevalent characteristic of bladder cancer." (PMID 39156764, 2024). "Chimeric RNA SLC2A11–MIF is upregulated and encodes a fusion protein in bladder cancer." (PMID 39156764, 2024). "In another study it was shown that chimeric transcript SLC2A11 (solute carrier family 2 member 11)–MIF promoted metastasis, proliferation and inhibited apoptosis in bladder cancer cells via PTBP1 (Polypyrimidine tract binding protein)-dependent mechanism." (PMID 41159021, 2025). "Targeting SLC2A11–MIF represents a promising and versatile therapeutic strategy for patients with bladder cancer." (PMID 39156764, 2024). "In our study, we focused on the highly prevalent chimeric RNA SLC2A11–MIF that facilitates the proliferation and metastasis of bladder cancer cells in vitro and enhances tumor growth and lymphatic metastasis in vivo." (PMID 39156764, 2024). "Targeting SLC2A11–MIF is a promising multipotent therapeutic strategy for impeding the proliferation and metastasis of patients with bladder cancer." (PMID 39156764, 2024). "Subsequently, functional investigations demonstrated that SLC2A11–MIF enhanced the proliferation, antiapoptotic effects, and metastasis of bladder cancer cells in vitro and in vivo." (PMID 39156764, 2024). "On the TCGA bladder cancer dataset, RTCpredictor re-identified three out of six known read-throughs (ACKR2-KRBOX1, CHCHD10-VPREB3 and SLC2A11-MIF)." (PMID 38796690, 2024). "A recently discovered chimeric RNA called SLC2A11–MIF has exhibited a high prevalence in cervical, colorectal, and bladder cancer." (PMID 39156764, 2024). "Consequently, targeting SLC2A11–MIF could serve as a therapeutic strategy for reducing the proliferation and metastasis of bladder cancer." (PMID 39156764, 2024).
colorectal cancer (3 papers, 2023 to 2024). A primary or metastatic malignant neoplasm that affects the colon or rectum. "On the TCGA colorectal cancer dataset, RTCpredictor re-identified five out of eleven known read-throughs (CTSD-IFITM10, GCSH-C16orf46, METTL21B-TSFM, SLC2A11-MIF and TRIM2-MND1)." (PMID 38796690, 2024).
breast carcinoma (1 paper, 2021). "Results showed that higher mRNA expression of SLC2A4 and SLC2A11 significantly associated with better prognosis of breast cancer patients (HR: 0.7 [0.55–0.88];p =0.0024 and HR: 0.45 [0.33–0.62];p =5E-07, respectively)." (PMID 34488531, 2021).
breast tumors (1 paper, 2023). "Specifically, SLC2A1, SLC2A6, SLC2A10, and SLC2A13 were significantly overexpressed, whereas SLC2A3, SLC2A4, SLC2A9, SLC2A11, and SLC2A12 had downregulated expressions in breast tumors compared with those in normal breast epithelium." (PMID 37108300, 2023).
chronic myelogenous leukemia (1 paper, 2021). "For instance, BCR-ABL in chronic myelogenous leukemia (CML), TMPRSS2-ETS, SLC45A3-ELK4, and D2HGDH-GAL3ST2 in prostate cancer, LHX6-NDUFA8 and SLC2A11-MIF in cervical cancer, RRM2-C2orf48 in colorectal cancer (CRC), and ASTN2-PAPPAas in esophageal cancer." (PMID 33805149, 2021).
tumor (5 papers, 2021 to 2025). "Additionally, lower levels of SLC2A3, SLC2A6, SLC2A9, SLC2A12, and SLC2A14 and higher levels of SLC2A1, SLC2A5, SLC2A10, and SLC2A11 had an association with advanced tumor stage." (PMID 36518662, 2022). "Significant overexpression of SLC2A1, SLC2A5, and SLC2A11 across various tumor types, including LUAD." (PMID 40824962, 2025). "Intriguingly, the growth, tumor size, and weight of the SLC2A11–MIF‐overexpressing tumors were significantly increased." (PMID 39156764, 2024). "Collectively, these findings provide compelling evidence supporting the role of SLC2A11–MIF in promoting tumor progression and metastasis in BCa cells in vitro and in vivo." (PMID 39156764, 2024). "Furthermore, knockdown of SLC2A11–MIF led to a significant decrease in tumor growth and reduced tumor size and weight." (PMID 39156764, 2024). "SLC2A1, SLC2A5, SLC2A10, and SLC2A11 levels tended to be higher in patients with advanced tumor stages, which shows that these molecules may be involved in the development of malignancies in LUAD patients." (PMID 36518662, 2022). "Based on the obtained results, we postulate that SLC2A11_ES_61347 may be correlated with tumor differentiation and may play a role in KIRC development." (PMID 34130646, 2021). "According to data from the UALCAN database, LUAD patients’ tumor tissues had hypomethylation of SLC2A1, SLC2A2, SLC2A5, SLC2A6, SLC2A7, SLC2A11 and hypermethylation of SLC2A3, SLC2A10, and SLC2A14 compared to normal tissues." (PMID 36518662, 2022).
cancer (4 papers, 2020 to 2024). A tumor composed of atypical neoplastic, often pleomorphic cells that invade other tissues. "Among nearby DEGs of differential chromatin accessibility, only the SLC2A11 and klotho (KL) genes were shown to be possibly involved in regulating mammalian ovarian activities while others have been largely implicated in regulating cancer cell proliferation and apoptosis." (PMID 32309280, 2020). "While SLC2A11 plays a crucial role in glucose absorption and is commonly observed in cancer cells due to its high energy demand, and MIF is involved in cell proliferation, tumorigenesis, and metastasis across multiple cancers." (PMID 39156764, 2024). "Our findings demonstrated the significant upregulation of SLC2A11–MIF in BCa cell lines, and this observation was further supported by The Cancer Genome Atlas (TCGA) data and an independent 94‐case cohort from Sun Yat‐Sen Memorial Hospital (SYSMH)." (PMID 39156764, 2024). "Notably, kidney has a key role in maintaining glucose homeostasis, and SLC2A11 as a novel, muscle-specific transport facilitator is a member of the extended GLUT family of sugar/polyol-transport facilitators, and this may be an additional source of energy for cancer." (PMID 34130646, 2021).
SLC2A11 also shares sentences with these, for which no sentence is quoted: cervical cancer (2 papers); esophageal cancer (2); esophageal squamous cell carcinoma (2); prostate carcinoma (2); congenital hemangioma (1); myeloma (1); non-small cell lung carcinoma (1); schizophrenia (1).